LAG3 (lymphocyte activating 3)
Diseases named in the same sentence as LAG3 in open-access papers (continued):
Sharing a sentence is not in itself a finding about the gene and the disease.
cancer (continued). "In previous researches, immune checkpoint inhibitors e.g., PD-L1, PD-L2, and LAG3, were proposed as treatments for cancer." (PMID 34244461, 2021). "Many LAG3 targeting immunotherapies clinically combined with antibodies against other IRs, such as PD-1/PD-L1, are used in cancer treatment." (PMID 33918146, 2021). "It was recently reported that FGL1 is a major ligand of LAG-3, which is normally secreted by the liver but is upregulated in several human cancers." (PMID 33633363, 2021). "LAG-3 is an emerging checkpoint target for cancer immunotherapy and further testing the responses of this subpopulation of cells is a focus of our future studies." (PMID 33597595, 2021). "The findings of our study indicate that the inhibition of both LAG-3 and PD-1/PD-L1 can enhance the anti-cancer response as part of a synergy." (PMID 34454491, 2021). "LAG-3 suppresses T cell activation and cytokine secretion and seems to work synergistically with PD-1 to inhibit immune responses, making anti-LAG-3 an important player in cancer immunotherapy." (PMID 33717075, 2021). "Other researchers found a striking synergy between LAG3 and PD-1 inhibitory pathways and argue that dual blockade of these molecules represents a promising combinatorial strategy to treat cancer." (PMID 34771650, 2021). "Lymphocyte activation gene-3 (LAG-3), being the most widely studied among them, is being explored as a target for the treatment of cancer patients." (PMID 33712537, 2021). "Consistently, the 5mC score was negatively related to PD-L1, PD-1, CTLA-4, and LAG-3 in all cancers in our study." (PMID 34836536, 2021). "Exhausted or dysfunctional T cells excessively exposed to infection or cancer antigens have a higher expression of LAG3 compared to naïve or activated ones." (PMID 34357118, 2021). "The potential benefit of targeting LAG-3 in cancer therapy is exemplified in the RELATIVITY-047 study." (PMID 34727262, 2021). "LAG-3 is the third inhibitory receptor to be exploited in human anti-cancer immunotherapies, and it is considered a potential next-generation cancer immunotherapy target in human therapy, right next to PD-1 and CTLA-4." (PMID 34067904, 2021). "LAG-3 expression can act as a compensatory mechanism that leads to therapeutic resistance of PD-1 blockade in cancer patients." (PMID 33712537, 2021). "LAG3 is also a potential target for cancer immunotherapy due to its negative regulatory role on T cells." (PMID 34249910, 2021). "Persistent antigen stimulation in cancer or chronic infection leads to chronic LAG-3 expression, promoting T cell exhaustion." (PMID 34298735, 2021). "Most literature has reported that MHC class II molecules are the main ligand used by cancer cells to bind LAG3 and thus reduce T cell activity." (PMID 33968077, 2021). "Recent evidence boosted the research of FGL1 in cancer biology by illustrating a new function of FGL1 in immune suppression where it acts as a major inhibitory ligand of LAG-3 and inhibits antigen-specific T cell activation." (PMID 34956878, 2021). "Therapeutic combinations of different types of LAG-3 monoclonal antibodies in combination with PD-1/PD-L1 inhibitors will be used for cancer treatment in the future." (PMID 34869005, 2021). "Here, we report on a single-domain antibody to evaluate whole-body LAG-3 expression in various syngeneic mouse cancer models using nuclear imaging." (PMID 33712537, 2021). "Lymphocyte-activation gene-3 (LAG-3) is a crucial immune checkpoint, involved in the regulation of T cell activation and proliferation in cancer patients and expressed on lymphocytes membrane." (PMID 34357118, 2021). "It has been reported that other inhibitory immune checkpoints like TIM‐3 and LAG‐3 become up‐regulated during PD‐1/PD‐L1 blockage, to resist treatment and allow cancer to progress." (PMID 33338327, 2021). "Combination therapies simultaneously targeting TIM-3, PD-1 and LAG-3 immune checkpoint have also been evaluated for advanced cancers (NCT04641871)." (PMID 35069581, 2021).
cancer (continued). "FGL1 is a major ligand of LAG3, which diminishes the function of T cells and immune evasion, and is upregulated in several human cancers; its expression is limited in most of the normal tissues and is associated with poor treatment outcomes." (PMID 33632231, 2021). "Cancer patients with high expression of LAG-3 in T lymphocytes show activated pro-apoptotic phenotypes in T cells, which is associated with increased PD-1 expression and poor survival after a PD-1 blockade." (PMID 34067904, 2021). "LAG-3 is commonly co-expressed with PD-1 in T cell exhausted cancers and contributes to resistance to immune checkpoint inhibitor therapy." (PMID 33805268, 2021). "Positive LAG-3 expression or the expression of both LAG-3 and PD-L1 has been associated with early cancer relapse." (PMID 34454491, 2021). "The results suggested that UBE2C expression was positively associated with the immune checkpoint-related genes in 31 cancers, which mainly included CD274, CTLA4, HAVCR2, LAG3, PDCD1, PDCD1LG2, SIGLEC15, and TIGIT." (PMID 34858987, 2021). "The observed correlations between promoter hypomethylation and LAG3 expression with resting DC infiltrates display the complex role of DCs in cancer immunology." (PMID 32861198, 2020). "We here applied an advanced droplet-based microfluidic assay to the evaluation of two novel checkpoint inhibitors, TSR-042-targeting PD1 and TSR-033-targeting LAG3, designed for cancer immunotherapy." (PMID 33188167, 2020). "Beyond these two receptors, preclinical data support a role for three other co-inhibitory receptors, TIM-3, TIGIT, and LAG-3, in cancer." (PMID 31974523, 2020). "The LAG-3 expression on CD8+ TILs is associated with decreased proliferation rates and production of effector cytokines in cancer." (PMID 33519815, 2020). "Several clinical trials (NCT02658981; NCT03489369; NCT02061761; NCT01968109; NCT03005782) are focusing on determining the safety and efficacy of LAG-3 targeted treatment of a wide range of cancers." (PMID 32640575, 2020). "Similar findings have been described in human cancers such as ovarian cancer and non-small cell lung cancer, where LAG-3 expression correlated with PD-1 expression in exhausted/dysfunctional T cells." (PMID 33027962, 2020). "Several more LAG3 targeted therapies are in preclinical development, aimed against cancer but also against autoimmune diseases." (PMID 32861198, 2020). "The aim of this review is to provide an overview of the biology of LAG-3 in the context of cancer as well as to provide an overview on the strategies used to detect and block LAG-3." (PMID 33374804, 2020). "Relatlimab is an anti-LAG-3 monoclonal antibody being investigated in several ongoing clinical trials, either alone or combined with PD-1 blockade, in various cancers." (PMID 32117298, 2020). "Preliminary results of LAG3 blockade in melanoma and other cancers are very promising, particularly in combination with other IC blockade and/or for refractory cases." (PMID 33488626, 2020). "T cell immunoglobulin and mucin domain-containing protein 3 (TIM-3) and Lymphocyte-activation gene 3 (LAG-3) are newly established T cell checkpoints and targets for cancer therapy, with studies suggesting an emerging role for these proteins in NK cells." (PMID 32290478, 2020). "Studies regarding different types of carcinomas have reported LAG3 expression in distinct T cell subsets." (PMID 32232506, 2020). "Recently, NK cells have emerged as contributors to the effect of inhibitors of T cell-related ICs like CTLA4, LAG3 or the PD1/PD-L1 axes in cancer patients, suggesting that these ICs also regulate the activity of NK cells under pathological conditions." (PMID 31998304, 2019). "In cancer patients, LAG3 is preferentially expressed on Treg TIL in the TME relative to those in the periphery." (PMID 31434339, 2019). "Soluble Lag-3 has been detected in the plasma of cancer patients and correlated with higher overall survival and disease free survival rates." (PMID 31192212, 2019).
cancer (continued). "Several ongoing clinical trials are exploring the therapeutic efficacy of LAG3 and PD-1 combined treatment with various advanced cancers." (PMID 31340613, 2019). "LAG-3 (CD223) is emerging as a potential target for cancer immunotherapy, due to its capacity of negatively regulating T cell activation and synergizing with PD-1 to exhaust T cells." (PMID 31340613, 2019). "Lymphocyte activation gene-3 (LAG3), an immune checkpoint up-regulated on activated T cells, Treg, and NK cells in different types of cancer, is required for the maintenance of Treg suppressive function." (PMID 30991686, 2019). "Of note, another immune-checkpoint molecule LAG-3 (Lymphocyte activation gene-3) is found to be differentially antigenic and upregulated in the cancer group." (PMID 31191821, 2019). "Recently, two murine cancer models showed that LAG3-blockade after IL-12 administration reduced metastases and increased number and functionality of NKs, implying a similar regulatory role for LAG3 on NKs as on T-cells." (PMID 30653605, 2019). "As LAG-3 blocking mAbs are currently tested in 28 different clinical trials for the treatment of cancer, we evaluated Nbs specific for the inhibitory immune checkpoint LAG-3 and used these for noninvasive imaging of moLAG-3." (PMID 31569553, 2019). "Immune checkpoint inhibitors, e.g., CTLA-4, programmed death- (PD-) 1, lymphocyte-activation gene 3 (LAG-3), and Tim-3, are today well recognized in the immune evasion of cancers." (PMID 31111075, 2019). "In this line, the FRACTION-GC trial seeks to further explore the potential of LAG-3 as a novel therapeutic target by including a group of cancer patients who will receive nivolumab plus an anti-LAG-3 antibody." (PMID 31662748, 2019). "Clinical trials are now underway to examine the effect of using a Lag-3 mAb (BMS-986016) in cancer patients either as a single agent or in combination with PD-1 blockade (Clinical Trials.gov: NCT02061761, NCT01968109)." (PMID 31192212, 2019). "The therapeutic efficacy of targeting TIM-3 and LAG-3 is currently under clinical investigation in a range of cancer patients." (PMID 31614877, 2019). "Other IC proteins are currently studied in preclinical and clinical settings as potential therapeutic targets in cancer, including LAG-3, TIM-3, and TIGIT." (PMID 31662748, 2019). "In multiple preclinical cancer models including AML, TIGIT expression was strongly associated with expression of other co-inhibitory molecules such as PD-1, Tim-3 and Lag-3, indicating the potential need for targeting multiple checkpoints in AML treatment." (PMID 29855615, 2018). "Accordingly, different LAG-3 antibodies as monotherapy or in combination with anti-PD-1 have entered clinical trials for various cancer entities focusing on solid tumors." (PMID 29535740, 2018). "What's more, in light of the interaction between LAG-3 and other immune checkpoints, targeting LAG-3 along with other checkpoints especially PD-1 holds considerable promise in cancer immunotherapy." (PMID 30603054, 2018). "CD8+ T cells, including CD45RA+CCR7+CD62L+CD8+ T cells, from cancer patient PBL contain elevated total LAG3 expression which correlated with stage and elevated expression of other IRs." (PMID 30400822, 2018). "The observed synergy of our LAG3 antibody with anti- PD-L1 agent indicated a great potential of this asset in the treatment of PD-1/PD-L1 refractory or resistant cancer patients." (PMID 30400822, 2018). "T-cell immunoglobulin-3 (CD366) was identified in 2002 and alongside TIGIT, LAG-3 represent the next generation of immune checkpoints in cancer immunotherapy." (PMID 29225597, 2017). "Pre-clinical studies with LAG3-Ig have shown that the mechanism acts mainly by favoring matured dendritic cells to favor Th1 responses; it has been used as adjuvant of cancer vaccines." (PMID 28934318, 2017). "The potential for LAG-3-driven immuno-modulatory responses are currently being explored for clinical cancer therapy." (PMID 28545567, 2017).
cancer (continued). "For example, simultaneously blocking PD-1 and LAG-3 was shown to be a promising immunization approach for cancer treatment." (PMID 28072682, 2017). "As a checkpoint inhibitor, LAG-3 depletion is currently in clinical trials for cancer immunotherapy." (PMID 28880895, 2017). "Taken together, this data indicates LAG3 acts as an immune-checkpoint receptor quenching the immune response, becoming a very attractive “druggable” receptor for cancer immunotherapy, especially in combination with PD1 and/or CTLA4 blockade." (PMID 28934318, 2017). "Some clinical trials have explored LAG-3 blockade to achieve tumor reduction and control cancer progress." (PMID 29312289, 2017). "Presently, LAG-3 has been shown to be an important immune regulator in autoimmunity, chronic viral infection, parasitic infection, and cancer." (PMID 29225597, 2017). "Accumulating data suggest that LAG-3 is involved in T cell exhaustion in various cancer and chronic infection settings." (PMID 29023417, 2017). "Reduction in the percentage of CD4+ T cells expressing PD-1, CD73, CD160, or LAG3 by LYC-54143 was observed in differentiated human Type 17 T cells using PBMCs from cancer patients as well as healthy donors." (PMID 28123897, 2016). "Anti-LAG-3 blocking mAb has recently entered clinical testing in cancer in monotherapy or in combination therapy with anti-PD-1 (NCT01968109)." (PMID 27415008, 2016). "In settings of chronic antigen exposure, such as cancer, expression of checkpoint receptors such as PD-1, CTLA4, TIM-3, LAG-3, and 2B4 have been associated with dysfunctional T cells, often termed exhausted or tolerized." (PMID 25614821, 2015). "Heterogeneity in intratumoral LAG-3 expression may explain the complex relationship between LAG-3 expression and cancer prognosis." (PMID 39751894, 2025). "IL-6-driven STAT3 signaling may also promote LAG-3 expression, as shown in cancer patient-derived naïve CD8 T cells." (PMID 39981237, 2025). "The flexibility of intervention offered by existing LAG3 antibodies, initially developed for cancer treatment, could expedite the development of neurodegenerative disease therapies." (PMID 39849529, 2025). "Blocking these interactions with monoclonal antibodies (Abs) targeting PD-1 (e.g., nivolumab, pembrolizumab), PD-L1 (e.g., atezolizumab, avelumab), CTLA-4 (e.g., ipilimumab), and more recently, Lymphocyte Activation Gene-3 (LAG-3) (e.g., relatlimab) has transformed cancer treatment." (PMID 40181971, 2025). "Notably, combining TLR agonists with immune checkpoint inhibitors such as PD-1/PD-L1, CTLA-4, TIGIT, and LAG3 has yielded synergistic effects and improved therapeutic outcomes across various cancer models." (PMID 41228373, 2025). "As LAG-3 inhibitors, such as relatlimab and eftilagimod, continue to reshape therapeutic paradigms, their integration with other immune-modulating agents holds great potential to advance the treatment of cancers." (PMID 41303538, 2025). "Interestingly, an in vitro model has shown that chemotherapy increased LAG-3 expression, which makes combining novel immune checkpoint inhibitors with conventional chemotherapy promising in difficult-to-treat cancers such as VHs." (PMID 40647508, 2025). "Immune checkpoint inhibitors targeting cell death ligand-L1(PD-L1), programmed cell death-1 (PD-1), cytotoxic T-lymphocyte antigen-4 (CTLA-4), and lymphocyte activation gene-3 (LAG-3) have substantially improved the cure and the management of several forms of cancer." (PMID 40149335, 2025). "LAG3-targeted therapies have become increasingly popular; many are in clinical trials for cancer." (PMID 39849529, 2025). "The elevated expression of LAG-3 in these cancers suggests its potential role in the immune evasion mechanisms of tumors, which may contribute to their progression and resistance to immune responses." (PMID 40606990, 2025).
cancer (continued). "Strikingly, ACACA expression exhibited significant negative correlations with the immune checkpoint-related genes (PDCD1, LAG3, LAGLS9, IDO1, CD244, CTLA4 and TIGIT), while showing positive associations with other genes (TGFBR1, KDR, IL10RB, CD160 and CD274) across most cancer types." (PMID 41169354, 2025). "The targets of ICIs approved for cancer treatment are PD-1/programmed death ligand 1 (PD-L1), cytotoxic T-lymphocyte associated protein 4 (CTLA-4), and lymphocyte activation gene-3 (LAG-3), and XPO1 inhibition has been shown to modulate the expression of these molecules." (PMID 40291981, 2025). "Therefore, the blockade of LAG-3 has shown promising therapeutic effects in various types of malignant tumors, and anti-LAG-3 immunotherapeutic agents have been utilized to restore T cell function." (PMID 40861801, 2025). "A study of LAG-3 as a potential immunotherapeutic target for microsatellite-stable, PD-L1+ endometrioid endometrial cancer has substantiated that LAG-3 may be a potential target for immunotherapy in this cancer." (PMID 40649775, 2025). "This contradicts the role of LAG3 as an immune checkpoint in other cancers, which may be due to the fact that LAG3 can play different roles depending on the activation status of the T cells." (PMID 39872846, 2024). "Lymphocyte activation gene 3 (LAG-3) has emerged as a promising target in cancer immunotherapy." (PMID 39743998, 2024). "The TIMER database was used to analyze differential expression of LAG3 at pan-cancer level." (PMID 38277212, 2024). "PD-1 and LAG-3 have been shown to be similar and generally co-expressed in cancer." (PMID 39796650, 2024). "To this end, we explored the mutation rate of the Tex signature genes in pan-cancer, and we observed a 2–3% SNV mutation frequency of PDCD1, LAG3, TIGIT, HAVCR2, and LAYN mainly in UCEC and SKCM, with HAVCR2 and TIGIT having the highest mutation frequencies (24% and 23% of samples, respectively)." (PMID 39064019, 2024). "In addition, CAR T cell therapy targeting LAG-3 provides another promising avenue for cancer treatment, particularly in solid tumors, where conventional immunotherapy does not respond well." (PMID 39660130, 2024). "Consequently, LAG3 is a major target for cancer immunotherapy with many anti-LAG3 monoclonal antibodies (mAbs) that block LAG3 inhibitory activity in clinical trials." (PMID 38556085, 2024). "Furthermore, they found a correlation between YY1 expression and LAG-3 expression within these ESCA cancer cells as well." (PMID 39796650, 2024). "This may be a promising approach to new methods that can be used to target LAG-3 in potential cancers." (PMID 39796650, 2024). "If agonist mAbs specific for PD1 or CTLA4 are also discovered, these may be combined with LAG3-specific agonist mAbs, either as separate molecules or as bispecifics, as is being done in cancer therapy." (PMID 38556085, 2024). "Gene and protein networks indicative of T-cell dysfunctionality could be extracted from PDCD1/LAG3 omics signatures in human cancers." (PMID 39030301, 2024). "The role of LAG-3 in inhibiting HBV-specific cell-mediated immunity in HCC could pave the way for new cancer treatments." (PMID 38890507, 2024). "It is also found that in HNSCC, LAG-3 expression could increase in the extracellular vesicles by miRNAs such as miR-7704 and miR-21-5p, suggesting that LAG-3 is a promising target for cancer." (PMID 38474377, 2024). "Finally, we gathered the IC50 of a wide variety of drugs among different cancer cell lines through the GDSC and CTRP databases and tried to explore the possible associations with the corresponding CXCL13, HAVCR2, LAG3, TIGIT, PDCD1, and LAYN mRNA values." (PMID 39064019, 2024). "When LAG-3 is inhibited, it can lead to a stronger T cell response to certain tissues like cancer." (PMID 39796650, 2024). "Furthermore, persistent antigen stimulation in cancer or chronic infection leads to chronic LAG-3 expression, promoting T cell exhaustion." (PMID 39796650, 2024).